IGF1 (insulin like growth factor 1)
Diseases named in the same sentence as IGF1 in open-access papers (continued):
Sharing a sentence is not in itself a finding about the gene and the disease.
dementia (continued). "As shown in volcano plots, 5,591 DEGs were selected in AD versus non-dementia controls, of which 2,805 were up-regulated and 2,786 were down-regulated; meanwhile, 6,742 DEGs were identified in IGF1-low versus high group, of which 3,366 were up-regulated and 3,376 were down-regulated." (PMID 35571248, 2022). "It is clear that the role of insulin/IGF-1 signaling in aging (beyond examining lifespan in worms, flies, and mice) should also be considered in light of the impact of this signaling pathway on dementia (cognition) and neurogenesis." (PMID 32226608, 2020). "Thus, the role of systemic IGF-1 on neurogenesis, cognition, and dementia deserves further analysis." (PMID 32226608, 2020). "Moreover, lower plasma concentration of IGF-1/IGFBP3 increased the risk of prevalent and incident dementia." (PMID 32312329, 2020). "Studying PD patients in advanced stages with dementia may further clarify the possible role of IGF-1 signaling in specific white matter disruptions." (PMID 30450079, 2018). "In the present study we have undertaken a more detailed analysis of the insulin and IGF-1 signaling pathway to dissociate the synergistic or additive connection between the early pathological events of dementia, such as high levels of Aβ and neuroinflammation, and the small focal ischemia." (PMID 29572520, 2018). "Follow-up studies are warranted to assess if IGF-1 is related to the development of dementia in PD." (PMID 29065116, 2017). "However, the association between IGF1 and the increased risk of dementia progression in different stages of AD has not been studied." (PMID 38687811, 2024). "That is, resistance exercise training seems to have greater effects on IGF-1 compared with aerobic exercise training in older adults, patients with MCI and dementia." (PMID 38961824, 2024). "While IGF-1 is mainly known for being a growth hormone that also increases testosterone production, evidence further suggests that IGF-1 plays an essential role in dementia, cardiovascular, and metabolic diseases." (PMID 38091084, 2024). "First, Stein and colleagues showed small-to-moderate effects of 12 weeks’ AEx compared to usual-care control on resting plasma BDNF (SMD = 0.31, 95%CI [−0.45, 1.05]) and IGF-1 levels (SMD = −0.61, 95%CI [−1.29, 0.10]) in 34 participants with mild-to-moderate AD dementia." (PMID 39328309, 2023). "The static relationship between the cGP/IGF-1 molar ratio and age in the PD-MCI group could be a transition phase prior to dementia." (PMID 36770687, 2023). "Findings from this study suggested that the effects of exercise on BDNF, irisin, IGF-1, and FGF-21 may be heterogeneous in older adults with mild-to-moderate AD dementia." (PMID 39328309, 2023). "Meanwhile, brain donors diagnosed with AD also showed lower levels of hippocampal IGF-1 expression than those with no dementia among individuals with TBI exposure." (PMID 31787098, 2019). "With conflicting potential mechanistic roles, IGF-1 has not been shown to be a good predictor of age-related disease outcomes such as cardiovascular disease, cancer or dementia." (PMID 28646237, 2017). "For instance, in the Framingham cohort (n = 3,582; aged 65 ± 11 years), participants with IGF-1 in the lowest quartile had a 51% greater risk of developing AD and higher IGF-1 concentrations were associated with greater brain volumes in those without dementia." (PMID 37608387, 2023). "It is also noteworthy that FoxO-mediated transcription is not the only mediator of the insulin and insulin-like growth factor-1 cascade, and that several factors might therefore be involved in the pathogenesis of dementia." (PMID 22761616, 2012).
Anxiety (72 papers, 2014 to 2026). Intense feelings of nervousness, tension, or panic often arise in response to interpersonal stresses. "Animal models have demonstrated associations between circulating IGF-1 level and brain injury-induced cognitive dysfunction and anxiety and suggest a neuroprotective role for IGF-1 in brain injury." (PMID 40697802, 2025). "A recent case-control study in China indicated that serum IGF1 concentration was negatively associated with chronic insomnia, sleep disorders and anxiety scores." (PMID 38800060, 2024). "These include studies showing induction of depressive-like behavior following IGF-1 deficiency, decreased depressive- and anxiety-like behavior after chronic FGF-2 treatment, and improved mood function following peripheral BDNF administration." (PMID 33269095, 2020). "Firstly, while Kendall’s Tau correlations between IGF-1 and GAD-7 for all TBI groups were strongly to very strongly negative, it appears that a history of preinjury anxiety may predispose individuals with TBI and low IGF-1 to more severe anxiety post-injury." (PMID 40697802, 2025). "Significant associations between IGF-1 levels and hypothymia, anxiety, and cognitive disturbances may indicate a pathogenic role of IGF-1 for the mentioned symptoms." (PMID 32384884, 2020). "These are being developed, and the recent pilot application of the frontal alpha band asymmetry index, a measure linked to anxiety and mood disorders, in a Rett syndrome trial testing full-length IGF-1 (mecasermin) suggests a good potential for EEG spectral analyses in FXS." (PMID 28616097, 2017). "Our results show that ICV injections of IGF-1 (total dose: 2 μg) reduce the anxiety and anhedonia disturbances in an ICVSTZ model of sporadic Alzheimer’s disease in rats." (PMID 40801621, 2025). "Other authors demonstrated that IGF-1 led to the facilitation of fear extinction memory consolidation, pointing to IGF-1 as a key regulator of anxiety and its potential role as a novel therapeutic target for the treatment of anxiety." (PMID 40801621, 2025). "In mice with anxiety resulting from hypothalamic axon damage, GH treatment enhanced IGF-1 and its receptor expression, supporting the survival and regeneration of hypothalamic neurons after injury, thus reducing anxiety symptoms." (PMID 39717701, 2024). "Several studies have shown that IGF-1 impacts the anxiety response, obsessive behavior, and depressive mood disorder." (PMID 38473814, 2024). "Intensive resistance training is effective in enhancing mood, reducing anxiety, and increasing insulin-like growth factor-1 serum concentrations, which is a mechanism for mood improvement in older individuals without clinical mood disorders." (PMID 39497901, 2024). "Although the IGF-1 concentration was appeared lower in the CID with anxiety group than in the CID group in our study, the difference was not statistically significant." (PMID 37151979, 2023). "Previous studies have revealed that IGF-1 concentrations are negatively correlated with anxiety levels, which is consistent with our results." (PMID 37151979, 2023). "Multiple high-confidence ASD risk genes associated with anxiety were dysregulated in our RNA-seq data including TMLHE and GRID2, DNAH10, GRIA1, SLC6A4, and IGF1." (PMID 37486945, 2023). "Increasing the serum IGF-1 levels (via clenbuterol treatment, a beta adrenergic agonist) and environmental enrichment resulted in anxiety behaviour returning to wildtype levels." (PMID 40656225, 2022).
Anxiety (continued). "Noteworthy, IGF1 levels were found inversely correlated with state anxiety; this finding, suggesting a state anxiety in patients with a greater disease control, need to be confirmed and better interpreted." (PMID 36165745, 2022). "In a phase 1 clinical trial of IGF-1 in RTT, improved right-sided alpha band asymmetry on electroencephalogram (EEG), a biomarker of anxiety and mood disorders, was mildly associated with lowered ADAMS scores in 5 out of 6 participants." (PMID 35568815, 2022). "Although preclinical studies suggest a role for IGF-1 in anxiety behaviour, clinical trials for IGF-1 have produced a complex picture, discussed by Singh and Santosh (2018)." (PMID 40656225, 2022). "The following mechanism(s) have been suggested for P4 effects in terms of reducing anxiety-like behavior: reducing glucocorticoid levels in the brain and increasing the IGF-1 levels." (PMID 33995946, 2021). "Insulin-like growth factor-1 (IGF-1) plays a key role in synaptic plasticity, spatial learning, and anxiety-like behavioral processes." (PMID 33792539, 2021). "Altogether, these results strongly support the potential role of IGF-1 as a new therapeutic target for the treatment of anxiety and mood disorders." (PMID 33792539, 2021). "In clinical trials, recombinant human IGF-1 can improve abnormal respiratory movement, cognitive ability, irritability, and anxiety in RTT patients." (PMID 32063830, 2020). "The most significant relationships were found between peripheral IGF-1 elevation and several DE symptoms – hypothymia, anxiety, and cognitive dysfunction." (PMID 32384884, 2020). "Participants engaging in exercise have observed increases in IGF-1, improved positive feelings and decreased anxiety." (PMID 31438638, 2019). "The reverse was also true in that blocking IGF-1 action early in life in animals housed under EE conditions negated the effects of the EE condition on later anxiety levels." (PMID 28238777, 2017). "IGF-1 treatment not only markedly reduced the right-sided abnormal asymmetry present in most subjects but these changes also correlated with reduction in anxiety severity." (PMID 28616097, 2017). "Similar results were obtained by injecting recombinant human IGF-1 in a mouse model, which improved respiratory patterns, reduced anxiety and increased exploratory behavior." (PMID 26877878, 2016). "The fact that anxiety-related scores were among the most responsive to IGF-1 in a recent trial emphasizes the importance of defining an adequate method for measuring this behavioral abnormality." (PMID 26379794, 2015). "Interestingly, insulin and Insulin-like Growth Factor (IGF-1) signaling in the amygdala has been shown to affect synaptic function and to influence anxiety-like behavior in mice." (PMID 40978196, 2025). "This suggests that IGF-1, through its anti-inflammatory, anti-anxiety, and antidepressant properties, may be a novel therapeutic agent for the treatment of neuropsychiatric disorders in sAD." (PMID 40801621, 2025). "The present results suggest that the improvements in spatial memory observed after ICVIGF-1 administration in the sAD model may also be attributed to IGF-1-induced reductions in anhedonia and anxiety and peripheral anti-inflammatory effects." (PMID 40801621, 2025). "Preclinical mouse models of Rett syndrome support this concept, as treatment of adult animals with mTOR-activating IGF-1 reduced anxiety levels and increased exploratory behaviors, suggesting that targeting mTOR can have an effect outside of the fetal developmental window." (PMID 38525876, 2024). "Notably, anxiety and phobias are common in children with autism spectrum disorders (ASDs), and it has been shown that the levels of IGF-1 in cerebrospinal fluid in children with ASD are significantly reduced." (PMID 38247874, 2024). "IGF-1 promotes hippocampal neurogenesis and can improve anxiety-like behaviors." (PMID 36383265, 2023).
Anxiety (continued). "In addition, serum IGF-1 was negatively correlated with anxiety behavior in mice measured 1 week after stress from the elevated plus maze." (PMID 36279393, 2022). "Indeed in rats, injection of IGF-1 early in life mimicked the effects of early life experience of EE when animals were run through an anxiety paradigm." (PMID 28238777, 2017). "Treatment with IGF-1 may similarly be applicable to autism-spectrum disorders for a wide range of symptoms such as memory, anxiety, hyperactivity, seizures and social behavior." (PMID 28954393, 2017). "Whereas the discovery GWAS of dog rivalry has no hits, the confirmation GWAS shows strong association with IGF1; and, unlike in the discovery GWAS, this locus is also significant in dog-oriented fear, separation-related anxiety, and touch-sensitivity." (PMID 27503363, 2016). "In rat pups, environmental enrichment during youth is also known to reduce anxiety-like behaviors during adulthood, but this effect of environmental enrichment is lost when IGF1 activity is blocked by systemic injection of blocking peptide during environmental enrichment." (PMID 24672476, 2014). "The mother suffers from anxiety and seizures, which may have limited the benefits of IGF1 treatment due to high stress levels being perceived by the patient." (PMID 24918098, 2014). "Moreover, central IGF-1 administration decreased anxiety levels in the EPM, demonstrated as more time spent in the open arms and the center of the maze at 7 and 90 days after injection concomitantly with a higher number of entrances to the open arms of maze at the early stage of sAD." (PMID 40801621, 2025). "Notably, the microglia-specific deletion of Igf1 during the first postnatal week had profound effects, leading to a significant decrease in both body and brain growth and ultimately resulting in adult animals exhibiting anxiety and neophobia." (PMID 38247874, 2024). "However, anxiety may affect IGF-1 in diverse ways, and further clarity will require further investigation." (PMID 37151979, 2023). "The PSQI score and IGF-1 concentration in the CID and CID with anxiety groups were higher than those in the control group." (PMID 37151979, 2023). "Among them, 65 patients with CID (35 of whom had anxiety) and 36 controls completed PSG and IGF-1 measurements." (PMID 37151979, 2023). "Thus, IGF-1 may play an important role in the amelioration of anxiety and memory deficits." (PMID 37151979, 2023). "Supplementing with exogenous active IGF-1 peptide and recombinant human IGF-1 can improve motor function, respiration, anxiety, and other behaviors, as well as prolong the life span of RTT mice." (PMID 32063830, 2020). "For the msTBI group with pre-morbid anxiety, there was a very strong, negative correlation between IGF-1 Z-score and GAD-7 scores that reached statistical significance (τ = −0.74, p = 0.0052)." (PMID 40697802, 2025). "For patients with mTBI and preinjury anxiety, a strong, negative correlation between IGF-1 Z-scores and GAD-7 scores that reached statistical significance was observed (τ = −0.68, p = 0.0002)." (PMID 40697802, 2025). "Data also suggest that anxiety experienced may generally increase with TBI severity and decreasing IGF-1 level, which may inform neuropsychological screening, monitoring, and treatment." (PMID 40697802, 2025). "For example, Xiao Chai Hu decoction may alleviate patients' anxiety symptoms by decreasing the levels of factors related to brain neurological function such as S100B, MBP, NSE and IGF-1." (PMID 38027586, 2023). "Clinical characteristics and IGF-1 in the patients with CID, CID with anxiety, and HC." (PMID 37151979, 2023).
Anxiety (continued). "Meanwhile, in mutant mice with low levels of serum IGF-I, adult hippocampal neurogenesis was lowered without showing a decrease in anxiety behavior by exercise, suggesting that IGF-1 is involved in exercise-induced neurogenesis." (PMID 34071457, 2021). "To determine whether the exploratory behavior resulted in part from increased stress or anxiety, we compared how much time CTR and Igf1 cKO mice spent in the more anxiogenic center of the arena vs. its less anxiogenic border." (PMID 30808767, 2019). "Decreased serum IGF-1 levels were reported in TBI patients, and in animal studies, circulating IGF-1 was correlated with brain injury-induced cognitive dysfunction and anxiety behaviors." (PMID 31787098, 2019). "Both tests did not reveal any difference between CTR and Igf1 cKO mice, indicating that the reduced exploratory behavior of Igf1 cKO mice does not reflect a difference in anxiety-like behaviors." (PMID 30808767, 2019). "The results of a short-term treatment consisting of a daily dose administered for 4 weeks showed that the use of IGF-1 is safe and it ameliorates irregular breathing and anxiety, although it did not improve intellectual disabilities." (PMID 26877878, 2016). "This study aims to evaluate whether intracerebroventricular (ICV) premedication with IGF-1 in a rat model of streptozotocin (STZ)-induced neuroinflammation can prevent the emergence of anhedonia and anxiety-like behavior by impacting the peripheral inflammatory responses." (PMID 40801621, 2025). "Moreover, the IGF-1 concentration was negatively correlated with participants’ anxiety score and sleep quality and positively correlated with stage N3 time during PSG, which indicates that IGF-1 may play an important role in insomnia and mood disorders." (PMID 37151979, 2023). "The apparent difference in IGF-1 concentration between the CID and CID with anxiety groups was not statistically significant." (PMID 37151979, 2023). "In conclusion, the serum IGF-1 concentration in patients with CID was lower than that in participants without CID, negatively correlated with anxiety score and sleep quality, and positively correlated with stage N3 time during PSG." (PMID 37151979, 2023). "The serum IGF-1 concentration in patients with CID was lower than that of participants without CID, negatively correlated with anxiety score and sleep quality, and positively correlated with stage N3 time." (PMID 37151979, 2023). "When patients were stratified according to their IGF1 × ULN, no relevant difference was found in the average scores for state and trait anxiety among patients with full disease control, partial disease control, and uncontrolled disease." (PMID 36165745, 2022). "Furthermore, among peripheral hormonal factors (IGF-1, FT4, DHEAS, E2, testosterone, cortisol), testosterone concentration at the first assessment was a negative predictor of depressive and anxiety symptomatology, both at the first assessment and after one year of intervention." (PMID 39519542, 2024).